MTOR (mechanistic target of rapamycin kinase)
Diseases named in the same sentence as MTOR in open-access papers (continued):
Sharing a sentence is not in itself a finding about the gene and the disease.
temporal lobe epilepsy (18 papers, 2012 to 2026). A localization-related (focal) form of epilepsy characterized by recurrent seizures that arise from foci within the temporal lobe, most commonly from its mesial aspect. "Rapamycin (mTOR inhibitor) reduced the seizure-induced rise of mTOR levels in rat brain tissues and reduced neuronal cell loss and mossy-fiber sprouting in pilocarpine and kainic (KA)-acid models of temporal lobe epilepsy (TLE)." (PMID 34832914, 2021). "The relevance of mTOR regarding temporal lobe epilepsy in animal models and patients has been rising in importance throughout." (PMID 37880579, 2023). "mTOR overactivation within the hippocampus is reported in the preclinical models of temporal lobe epilepsy." (PMID 34832914, 2021). "The relevance of mTOR regarding temporal lobe epilepsy in animal models and patients has been rising in importance throughout the last decade." (PMID 27855659, 2016). "Specifically, excessive mTOR signaling through a mutation in the tuberous sclerosis complex (TSC1/2) leads to hippocampal hyperexcitability linking mTOR with temporal lobe epilepsy." (PMID 27855659, 2016). "Low Kv1.1 levels are associated with increasing seizure frequency in kainate induced temporal lobe epilepsy in rats, correlating with high mTOR levels." (PMID 27855659, 2016). "Growing evidence from rodent models of temporal lobe epilepsy (TLE) indicates that dysregulation of the mammalian target of rapamycin (mTOR) pathway is involved in seizures and epileptogenesis." (PMID 22761730, 2012). "Therefore, it is possible that hyperactivation of mTOR within reactive astrocytes reduces extracellular glutamate clearance, potentially resulting in enhanced excitability and temporal lobe epilepsy progression." (PMID 34658792, 2021). "Moreover, other studies have shown that IL-1β regulates the PI3K/Akt/mTOR signalling pathway to generate mesio-temporal lobe epilepsy (MTLE)." (PMID 30514296, 2018). "In addition to its pivotal role in the pathogenesis of TSC, mTOR dysfunction also plays a role in other neurologic disorders, both genetic (hemimegalencephaly, focal cortical dysplasia) and acquired (temporal lobe epilepsy, traumatic brain injury)." (PMID 28367137, 2017).
ZIKV infection (18 papers, 2017 to 2024). "Genes included in these categories usually undergo differential expression profiles during ZIKV infection mostly associated with extracellular matrix, cell adhesion, collagen-encoding as well as mTOR and Wnt pathways." (PMID 34125832, 2021). "ZIKV infection of human fetal neural stem cells (fNSCs) was found to cause inhibition of the Akt-mTOR pathway, leading to defective neurogenesis and aberrant activation of autophagy." (PMID 29762492, 2018). "Initial autophagy induction (with limited viral replication during a brief period of <24 h post infection) was followed by mTOR activation and subsequent down regulation of autophagy with associated increased viral replication later in the course of ZIKV infection." (PMID 37431450, 2021). "ZIKV infection of human umbilical vein endothelial cells can modulate the AKT/mTOR and BECN1 signalling pathways to induce autophagy and enhance viral replication." (PMID 37936178, 2023). "ZIKV infection also activates mTOR complex I (mTORC1) and mTORC2 in neuronal and glial cells, and mTOR inhibition reduces ZIKV protein expression and the production of infectious particles." (PMID 37820117, 2023). "ZIKV infection activates the mechanistic (mammalian) target of rapamycin (mTOR) pathway, a master regulator of autophagy, impacting neurogenesis." (PMID 37820117, 2023). "For instance, ZIKV infection of human foetal neural stem cells can trigger autophagy by inhibiting the AKT/mTOR signalling pathway." (PMID 37936178, 2023). "To further test for the role of mTOR signaling in ZIKV infection of NPCs, we used an inhibitor and an activator of the pathway." (PMID 29396410, 2018). "This indicates that autophagy induced by ZIKV infection is regulated by the class I PI3K/Akt/mTOR pathway." (PMID 29762492, 2018). "Prior to Zika virus (ZIKV) infection the NPCs from CZS babies show a significantly different gene expression signature of mTOR and Wnt pathway regulators, key to a neurodevelopmental program." (PMID 29396410, 2018). "Another pathway in which PPAR-γ may play a relevant role in the pathophysiology of the ZIKV infection is the PPAR-γ/mTOR signal pathway." (PMID 37376550, 2023). "Likewise, the ratio of Ser556–phosphorylated ULK1 to total ULK1 was also increased after ZIKV infection, whereas the ratios of Ser2448–phosphorylated mTOR to total mTOR and Ser757–phosphorylated ULK1 to total ULK1 were decreased." (PMID 36405969, 2022). "However, non-affected twins’ NPCs treated with rapamycin showed a similar PFU/mL to that observed in non-treated cells from the affected twins supporting that mTOR individual response is an important factor for successful ZIKV infection." (PMID 29396410, 2018). "Importantly, in line with previous studies pointing to a role of NS4A and NS4B in inhibition of neurogenesis and deregulation of the Akt-mTOR signaling pathway, this study also identified shared targets deregulated both by ZIKV infection and NS4B expression (e.g., MAP2, -6, DPYSL3, -5, CNTN2)." (PMID 31546825, 2019). "The activities of mammalian target of rapamycin (mTOR) at Ser-2448 and ULK1 at Ser-757 were suppressed independently of AMPK during ZIKV infection." (PMID 36405969, 2022). "The effects of AMPK silencing on ZIKV infection and the ULK1 and mTOR signaling pathways, two pathways downstream of AMPK, were evaluated via western blotting." (PMID 36405969, 2022). "In this study, increased phosphorylation of ULK1-Ser556 and reduced phosphorylation of mTOR-Ser2448 and ULK1-Ser757 were observed along with increased AMPK activity after ZIKV infection." (PMID 36405969, 2022). "A previous study has shown that ZIKV infection induces autophagy in human fetal neural stem cells via its NS4A and NS4B proteins by deregulating Akt-mTOR signaling." (PMID 29762492, 2018). "Moreover, ZIKV infection increased Ser556 phosphorylation of ULK1 and significantly reduced Ser2448 phosphorylation of mTOR and Ser757 phosphorylation of ULK1." (PMID 36405969, 2022).
ZIKV infection (continued). "In addition, transcriptome profiling revealed a different pattern in NPCs from CZS-affected as compared to CZS-non-affected individuals highlighting the role of Wnt and mTOR signaling in modulating ZIKV infection outcome." (PMID 29396410, 2018).
anaplastic thyroid cancer (17 papers, 2015 to 2025). "Notably, a recent case report in anaplastic thyroid cancer suggests that MTOR mutation is a mechanism of acquired resistance to rapalog therapy." (PMID 26255626, 2015). "In anaplastic thyroid cancer (ATC), whole exome sequencing showed 9% of somatic point mutations (R164Q and M2327I) in the mTOR gene." (PMID 36980552, 2023). "This shows that PAC inhibits the mTOR pathway in anaplastic thyroid cancer cells." (PMID 36918686, 2023). "Although PI3K/Akt/mTOR signaling has been corroborated to increase chemotolerance of cancer cells, such as PC and anaplastic thyroid carcinoma, documentations that elucidated the collaborative role of SRPX2 and PI3K/Akt/mTOR signaling in regulating PC chemosensitivity were scarce." (PMID 33336063, 2020).
clear cell carcinomas (17 papers, 2012 to 2025). "The inhibition of the mTOR pathway prevented clear cell carcinoma cells from acquiring resistance to trabectedin." (PMID 38758230, 2024). "As inferred by enrichment of PIK3CA somatic mutation, clear cell carcinomas demonstrated superior sensitivities to PAM pathway inhibitors, including BKM120 (PI3K, P = 1.88 × 10−03) and AZD2014 (mTOR, P = 2.25 × 10−03)." (PMID 31771620, 2019). "Moreover, an increased activation of the mTOR cell signaling pathway was described in trabectedin-resistant clear cell carcinoma cell lines, while trabectedin treatment induced a prolonged stimulation of mTOR in the same model." (PMID 38758230, 2024). "Interestingly in about 87 % of 52 tested clear cell carcinomas elevated mTOR activity is observed." (PMID 27090655, 2016). "A subset of clear cell carcinomas also harbored alterations in PIK3CA/PTEN/AKT pathway, particularly PTEN, indicating a potential benefit of PI3K/Akt/mTOR inhibitors." (PMID 32279409, 2020). "A subset of clear cell carcinomas also harbored alterations in this pathway, particularly PTEN, indicating a potential benefit of PI3K/Akt/mTOR inhibitors." (PMID 32279409, 2020). "Currently, three major categories of systemic treatment exist for the largest subgroup of mRCC, the clear cell carcinomas: cytokines and immune checkpoint inhibitors, anti VEGF targeted drugs and mTOR inhibitors." (PMID 28859644, 2017). "MiR-100 represses mTOR (mammalian target of rapamycin) signaling and increases sensitivity to the cancer drug everolimus (rapamycin analog RADOO1) in cell lines derived from clear cell carcinomas." (PMID 23978303, 2013). "The GOG recently completed accrual of patients for a front-line, phase II study of temsirolimus, an mTOR inhibitor, used following paclitaxel/carboplatin as a first-line therapy in treating patients with newly diagnosed stage III/IV clear cell carcinoma (GOG-268)." (PMID 30971221, 2019). "miR-100 represses mTOR (mammalian target of rapamycin) signaling and increases sensitivity to the cancer drug everolimus (rapamycin analog RAD001) in cell lines derived from clear cell carcinomas." (PMID 23237306, 2012). "Because of the lack of available treatments, studies combining non-clear and clear cell carcinomas have focused on angiogenesis inhibitors (anti-VEGF) and other targeted therapies (mTOR inhibitors)." (PMID 30386718, 2018).
gestational diabetes (17 papers, 2017 to 2026). Carbohydrate intolerance first diagnosed during pregnancy. "Of note, neonatal hypoglycemia could be found in both acquired causes (e.g., newborn of a mother with gestational diabetes) and genetic syndromes [e.g., Beckwith-Wiedemann syndrome (BWS) and some mTOR-related disorders]." (PMID 35096710, 2021). "We also argue that this regulatory system responds to nutritional cures in the opposite direction, i.e., overnutrition in conditions such as maternal obesity and gestational diabetes, where placental mTOR signaling activation may contribute to fetal overgrowth in some cases." (PMID 40534504, 2025). "In an in vitro model of gestational diabetes mellitus, Klotho was found to be involved in the insulin resistance of trophoblast cells, partially mediated through the IGF1/phosphatidylinositol 3-kinase (PI3K)/Akt/mammalian target of rapamycin (mTOR) pathway." (PMID 38486352, 2024).
glomerular disease (17 papers, 2012 to 2026). "Conversely, the genetic inhibition of mTOR in podocytes has been associated with glomerular diseases, resulting in early-onset FSGS in rodent models." (PMID 41509918, 2026). "Both mTOR signaling and autophagy are important modulators of podocyte homeostasis, regeneration, and aging and have been implicated in glomerular diseases." (PMID 35805186, 2022). "As well as its metabolic regulatory function, mTOR signalling has been implicated in the pathogenesis of various glomerular diseases including diabetic nephropathy and crescentic nephritis." (PMID 35290515, 2022). "It was found that the expression of mTOR in renal tissues of patients with glomerular disease and animal models was significantly increased mTOR plays a gating role in autophagy." (PMID 38567351, 2024). "Rapamycin, an inhibitor of mTOR signaling, has been proven to be an effective therapeutic approach in animal models of glomerular disease and in clinical studies." (PMID 35149934, 2022). "Data also suggest a role for mTOR signalling in both podocyte adaptation and the development and progression of glomerular disease." (PMID 35290515, 2022). "Several prior studies have shown that podocyte injury is closely related to the activation of the mammalian target of rapamycin (mTOR), which plays an important role in glomerular disease." (PMID 35149934, 2022). "Hamatani and colleagues observed activation of the mammalian target of rapamycin (mTOR), a main player in cell proliferation and survival, specifically in PECs in experimental models of glomerular diseases." (PMID 32444668, 2020). "By shuttling between the nucleus and the cytoplasm, SRSF1 interacted with and activated mTOR to promote translation 22, 23, 48; dysregulation of the latter was sufficient to facilitate glomerular diseases." (PMID 28444861, 2017). "In glomerular disease, short-term activation of mTOR signaling has a positive effect, but long-term activation leads to proteinuria and glomerulosclerosis." (PMID 27338360, 2016). "Among the triggered intracellular pathways involved in mesangial cell proliferation, the mammalian target of rapamycin (mTOR) plays a critical role in cell growth, in turn regulated by many cytokines, disbalanced by the altered glomerulopathy itself." (PMID 22685654, 2012). "Whilst this study highlights age-related differences in mTOR expression and podocyte adaptability, how this plays out in the setting of glomerular disease remains unknown and warrants further investigation." (PMID 35290515, 2022). "Several studies have described a role for mTOR in glomerular disease models." (PMID 32444668, 2020). "Another target of TTX in glomerular disease could also be the mTOR pathway, which has been demonstrated to have an important role in podocyte homeostasis." (PMID 30736354, 2019). "The findings of three different studies revealed that the mechanistic target of rapamycin (mTOR) signaling plays an important role in the physiology and phenotype of PECs and that changes in mTOR activity can trigger PEC activation or necrosis in experimental glomerular disease." (PMID 28361304, 2017). "However, the study of mTOR also showed that both signaling and its inhibition are ambivalent and context-dependent, and a better understanding of the signaling network will be needed to enable the design of a mTOR-targeted therapy for glomerular disease." (PMID 23372691, 2013). "Further studies, including the functional perturbation of the p38 pathway, are needed to assess whether targeting the p38-mTORC1 crosstalk could alleviate glomerular disease in states of mTOR hyperactivation independent of PHB2 deficiency." (PMID 41509918, 2026).
hemangioma (17 papers, 2007 to 2025). A benign vascular lesion characterized by the formation of capillary-sized or cavernous vascular channels. "Sirolimus, an mTOR inhibitor, has emerged as a promising second-line option, particularly for propranolol-resistant diffuse lesions or hemangiomas associated with PHACE syndrome." (PMID 41574351, 2025). "Low-concentration rapamycin has also demonstrated efficacy in inhibiting hemangioma endothelial cell proliferation and migration both in vitro and in vivo by reducing the activation of the protein kinase B/mTOR/S6 signaling pathway." (PMID 40428263, 2025). "Both sirolimus and everolimus, as mTOR inhibitors, have demonstrated anti-proliferative and anti-angiogenic effects in in vitro studies of hemangioma endothelial cells, suggesting their potential role in the treatment of infantile hemangiomas(IHs)." (PMID 40356783, 2025). "Sirolimus is considered an effective drug for the treatment of hemangioma by inhibiting the mTOR pathway, and a few cases of sirolimus in the treatment of hemangiomas have been infrequently reported." (PMID 36937450, 2023). "Rapamycin, an mTOR inhibitor, has been shown to inhibit HemSC self-renewal and vascular differentiation potential in patient-derived hemangioma stem cells." (PMID 27786256, 2016). "In particular, tsc1+/- or tsc2+/- mutant mice which are characterized by high level of mTOR-mediated phosphorylation of Eif4ebp1 and Rps6kb1, have hemangiomas with poorly developed vasculature that are prone to rupture." (PMID 17892597, 2007). "Linc00152 knockdown exerts a potent anti-hemangioma effect by inactivating the Akt/mTOR pathways." (PMID 34362467, 2021). "Above findings indicate that it is possible for proanthocyanidins, as a potential antiangiogenesis candidate, to prevent hemangioma angiogenesis through targeting the HIF-1/VEGF signals via inactivating PI3K/Akt pathway along with their downstream components mTOR/p70S6K." (PMID 33490272, 2021). "However, abnormal activation of PI3K/Akt signaling pathway significantly inhibits the spontaneous apoptosis of hemangioma endothelial cells during hypoxia through modulating the downstream components mTOR and p70S6K." (PMID 33490272, 2021). "Recent studies suggest that ID-1 knock-down in endothelial cells derived from angioma inhibits proliferation and induces apoptosis by inhibiting PI3K/Akt/mTOR signaling." (PMID 34440702, 2021). "In hemangiomas, the binding of VEGF-A with VEGFR-2 stimulates the mTOR pathway resulting in increased cell proliferation and survival of endothelial cells." (PMID 34824953, 2021). "In the tumorigenesis of concurrent schwannomas and hemangiomas, an essential role is played by the embryogenetic pathway, VEGF pathway, mTOR pathway, MAP kinase pathway, and tuberin/hamartin interactions with Rheb1/KREV1RAP1A." (PMID 34824953, 2021). "Previous studies have shown that the mTOR pathway is activated at sites of inflammation in RA and that activation of the mTORC1 pathway regulates FABP4 expression in hemangiomas;22,23 however, it remains unclear whether activation of the mTORC1 pathway regulates FABP4 expression in RA." (PMID 35729106, 2022).